ANKRD22 (ankyrin repeat domain 22)
Diseases named in the same sentence as ANKRD22 in open-access papers (continued):
Sharing a sentence is not in itself a finding about the gene and the disease.
cancer (14 papers, 2017 to 2025). A tumor composed of atypical neoplastic, often pleomorphic cells that invade other tissues. "Hopefully, this study will not only provide the fundamental concepts of ANKRD22's role in PC and even metastatic PC but also place the first brick for the invention of ANKRD22-targeted anti-cancer therapy." (PMID 40225855, 2025). "For instance, combining therapies targeting ANKRD22 with drugs that modulate lipid metabolism pathways, such as orlistat, holds promise in improving cancer treatment outcomes." (PMID 39021049, 2024). "ANKRD22, a protein featuring four ankyrin repeat (ANKR) motifs, has been implicated in the development of various cancers." (PMID 39021049, 2024). "The membrane topology and intracellular localization of ANKRD22, a novel human N-myristoylated protein with a predicted single-pass transmembrane domain that was recently reported to be overexpressed in cancer, were examined." (PMID 34584137, 2021). "Further studies are required to clarify the physiological function of ANKRD22 and the role of LD localization of this protein in the progression or suppression of cancer." (PMID 34584137, 2021). "ANKRD22 plays a dual role in cancer development as a cancer suppressor or tumor supporter." (PMID 40225855, 2025). "The overexpression and copy number amplification of ANKRD22 and LIPM in early cancer, and overexpression, mutation, and copy number amplification of IGHA1 in early cancer may all promote early metastasis." (PMID 37152984, 2023). "ANKRD22 is a functionally unknown protein that was recently reported to be overexpressed in cancer such as non-small cell lung, colorectal, and breast cancer." (PMID 34584137, 2021). "Thus, in many types of malignant cancers, ANKRD22 may play important roles in the procession of progression of cancer through several mechanisms." (PMID 34584137, 2021). "As a result, ANKRD22, a functionally unknown protein with a predicted single-pass transmembrane domain that was recently reported to be overexpressed in cancer, was found to be an N-myristoylated hairpin-like monotopic membrane protein specifically localized to lipid droplets (LD)." (PMID 34584137, 2021). "Furthermore, it is interesting to note that upregulation of genes, such as ANKRD22, FRMD6, and KIR3DL2, and down-regulation of genes, such as TIMP3, SAP25, NAPSA, and TIMP are associated with a worse prognosis in cancer, are also associated with a worse prognosis in AdHF." (PMID 29236770, 2017). "Bioinformatics analysis demonstrated that ANKRD22 and NOG can serve as potential biomarkers for the progression of cancers." (PMID 36035194, 2022). "However, the role of LD localization in cancer progression mediated by ANKRD22 is unknown." (PMID 34584137, 2021). "Thus, the effects of ANKRD22 on cancer may differ among cancer types." (PMID 34584137, 2021). "However, when we investigated EPHX4 and ANKRD22 expression in different pathological tumor stages, EPXH4 did not statistically significantly express across cancer stages, F = 1.06, p > 0.05, whereas ANKRD22 showed that its presence between tumor stages was significant with F = 4.8 and p < 0.01." (PMID 40225855, 2025).
tumor (12 papers, 2017 to 2025). "whereas the downregulated genes induced by CFP1 deficiency, such as FAM83A and ANKRD22, were upregulated in tumor tissues and associated with poor prognosis in the TCGA LUAD dataset." (PMID 37735441, 2023). "In the present study, we identified ANKRD22 as a novel tumor-associated gene in non-small cell lung cancer (NSCLC)." (PMID 28667340, 2017). "The present study shows, for the first time, that there is an association between the up-regulation of ANKRD22 and tumor progression in NSCLC." (PMID 28667340, 2017). "Furthermore, as ANKRD22 is localized in the mitochondria, it implies a potential association with tumour metabolism." (PMID 39021049, 2024). "Therefore, we screened out the novel tumor-associated gene, ANKRD22, which was successively up-regulated during tumor progression and influenced tumor cell growth in NSCLC." (PMID 28667340, 2017). "Therefore, aberrant high expression of ANKRD22 was significantly associated with increased tumor progression and shortened OS time in NSCLC." (PMID 28667340, 2017). "Intriguingly, we found that ANKRD22 expression was statistically significantly different across tumor stages." (PMID 40225855, 2025). "ANKRD22, situated on chromosome 10q23.31, is a protein featuring four ANKR motifs and has been implicated in the development of various tumours." (PMID 39021049, 2024). "Developing METTL14‐based inhibitors targeting ANKRD22 to impede lipid metabolism in tumour cells emerges as a promising strategy for future NPC treatment." (PMID 39021049, 2024). "In xenograft experiments, knockdown of ANKRD22 or in vivo treatment with ANKRD22 siRNA inhibits tumor growth." (PMID 33536349, 2021). "Recently, studies demonstrated that ANKR protein facilitated the development of non-small cell lung cancer (NSCLC), but suppressed the development of prostate cancer, suggesting that ANKRD22 exerts pro-tumor or anti-tumor effects in different tumor types." (PMID 32651974, 2021). "Gene knockdown and overexpression analyses have shown that ANKRD22 promotes tumor progression via increasing cell proliferation." (PMID 33536349, 2021). "The ANKRD22/E-Syt1 axis is a potential therapeutic target as it is central to the reprogramming of CRC cells induced by tumor environment." (PMID 31903135, 2020). "In summary, this is the first report to demonstrate that ANKRD22 exhibits oncogene activity that promotes tumor progression in NSCLC through the transcriptional regulation of E2F1." (PMID 28667340, 2017). "Knockdown and overexpression analysis revealed that ANKRD22 promoted tumor progression by increasing cell proliferation." (PMID 28667340, 2017). "Remarkably, direct injection of ANKRD22 small interfering RNA (siRNA) into xenograft tumors inhibited tumor growth." (PMID 28667340, 2017). "The results showed that ANKRD22-shRNA induced silencing of ANKRD22 resulting in a significant decrease in tumor volumes and weights compared with control-shRNA." (PMID 28667340, 2017). "In xenograft assays, knockdown of ANKRD22 or in vivo treatment with ANKRD22 siRNA inhibited tumor growth." (PMID 28667340, 2017). "As shown in IPA analysis, we pinpointed that upon its high expression, ANKRD22 might activate specific metastatic traits encompassing migration and invasion of tumor cells." (PMID 40225855, 2025). "Owing to the results, such as ANKRD22 remarkably expressed in the tumor group, potentially contributing to the NF-kB pathway and metastatic process, the qPCR and western blot could be conducted to investigate relevant components." (PMID 40225855, 2025). "However, the regulatory mechanisms and functions of ANKRD22 in tumour cell metabolism reprogramming during tumorigenesis remain poorly understood." (PMID 39021049, 2024). "However, ANKRD22 expression was correlated with LN metastasis (p = 0.016*), vessel invasion (p = 0.028*), tumor-node-metastasis (TNM) stage (p = 0.020*), and tumor grade (p = 0.019*)." (PMID 32651974, 2021).
tumor (continued). "Moreover, in vivo treatment with ANKRD22 siRNA decreased the size of xenograft tumors, suggesting that inhibition of ANKRD22 significantly inhibits tumor growth." (PMID 28667340, 2017). "Furthermore, in order to examine the effects of RNAi silencing ANKRD22 gene on the tumor inhibition, mixture of ANKRD22-siRNA and atelocollagen was directly injected into luciferase labeled xenograft tumors with approximately 10 mm in diameter." (PMID 28667340, 2017). "Thus, NF-kB might be a promising pathway that ANKRD22 might exploit for PC tumor initiation." (PMID 40225855, 2025). "IHC results showed that, compared to adjacent non‐tumour NPE, ANKRD22 protein was highly expressed in NPC tissues." (PMID 39021049, 2024). "Ankyrin repeat domain 22 (ANKRD22), a member of the ankyrin repeat (ANKR) family, is constitutively expressed in normal digestive tract epithelium and in tumor cells." (PMID 32651974, 2021). "The mRNA expression levels of COL17A1, CEP55, KLK10, MET, ITGB6, ANKRD22, and ARNTL2 were significantly increased in PAAD tumor tissue." (PMID 31612115, 2019). "The downregulated MCOLN3 and SLC25A45 with HR < 1 were considered as tumor suppressors, whereas the upregulated COL17A1, CEP55, KLK10, MET, ITGB6, ANKRD22, and ARNTL2 with HR > 1 were regarded as oncogenes." (PMID 31612115, 2019). "In addition, we assessed the expression of molecules such as ANKRD22, GINS3, POLE2, PLEK2, FERMT1 and METTL14 in subcutaneous tumours and lung metastatic tissues." (PMID 39021049, 2024). "In addition, high levels of HCST, C3AR1, GBP4, LY96, ANKRD22, FPR3 and FCGR2A, have also been related to immune activation and/or inflammatory response in tumours; however, their role in basal-like breast malignancies are yet to be uncovered." (PMID 28351365, 2017).
neurodegenerative disease (1 paper, 2021). A disorder of the central nervous system characterized by gradual and progressive loss of neural tissue and neurologic function. "Studies regarding the transcriptomic alterations of ANKRD22 in patients with PD are limited and the mechanisms by which ANKRD22 transcriptomic alterations contribute to neurodegenerative diseases are poorly understood." (PMID 34574038, 2021).
ANKRD22 also shares sentences with these, for which no sentence is quoted: hepatocellular carcinoma (2 papers); lung cancer (2); nasopharyngeal carcinoma (2); pulmonary TB (2); endometrial carcinoma (1); infection (1); infertile (1); inflammatory bowel disease (1); ischemic stroke (1); Onset (1); Parkinsonism (1); respiratory diseases (1); sarcoidosis (1).